CD24 (CD24 molecule)
Diseases named in the same sentence as CD24 in open-access papers (continued):
Sharing a sentence is not in itself a finding about the gene and the disease.
cancer (continued). "Using the appropriate antibodies and the flow cytometry method, cancer stem cells with the CD44(+) CD24(+) phenotype were identified in each material." (PMID 38201547, 2023). "As a strong anti-phagocytic “don’t eat me” signal, CD24 can help cancer cells avoid being attacked by macrophages that express Siglec-10." (PMID 37846296, 2023). "We also analyzed the expression of cancer stem cell markers ALDH1A1, CD24, and CD44, which are often associated with EMT induction." (PMID 37834189, 2023). "High expression of CD24, CD47, and CD155 was associated with short overall survival (OS) in cancers." (PMID 38016957, 2023). "Copious literatures recently describing CD24 overexpressed in various types of carcinoma, which were evident in many gene profiling analyses using microarray technology." (PMID 37919766, 2023). "CD24-based cancer immunotherapy was originally reported decades ago for a subgroup of patients with B-lymphoproliferative disorders." (PMID 35625912, 2022). "Notably, high expression of CD24 has been associated with poor prognosis in several cancers, an association that might be partially related to its checkpoint function on innate anti-cancer immunity." (PMID 35625912, 2022). "Sialyl-Lewisx, an abundant sialylated epitope on cancer cell CD24, is an important factor in P-selectin binding and is implicated in breast, ovarian, and lung cell metastasis." (PMID 36294907, 2022). "Cancer Stem Cells (CSCs) that express CD44+/CD24- can contribute to chemoresistance and a poor prognosis." (PMID 36274112, 2022). "CD24 has been extensively studied in the context of cancer biology, with it being defined as a cancer stem cell marker in various malignancies, such as breast, pancreas, and ovarian carcinoma." (PMID 35625912, 2022). "In this setting, we observed that IFN-I favors the enrichment of rare CD133+CD24+CD44+ putative CSCs (IFN–CSCs) in all analyzed murine cancer cell lines." (PMID 36002648, 2022). "Eleven of those proteins were detected in all patients, including the common EV markers CD9, CD63 and CD81, cancer-related markers CD24, CD29, CD44 and CD146, platelet markers CD41b, CD42a and CD62p as well as HLA-DR/DP/DQ." (PMID 35012489, 2022). "When remaining cancer cells were counted in phagocytosis assays after 2 h, treatment with CD24 mAb SN3 almost completely removed UPN-1 cells from the solution, with an ~93% removal rate." (PMID 35625912, 2022). "CD24 is known to be a surface marker of cancer stem cells, demonstrating a high ability to self-renew and enhance therapy resistance." (PMID 36552039, 2022). "Although newly uncovered in the context of cancer, such immune checkpoint activity of the CD24/Siglec-10 axis on innate immune cells has been well established in the context of apoptotic cell removal and infection." (PMID 35625912, 2022). "In other CD24+ cancer entities (origin: bladder, prostate, kidney, skin, lung, liver, brain, and ovary), we found a similar expression profile with predominant expression of ENST00000606017.1 and very weak expression of ENST00000619133.4." (PMID 34293822, 2022). "Cancer cells were characterized by strong expression of canonical mammary epithelial cell markers, Epcam and Cd24, and including luminal markers Krt8 and Krt18, consistent with the luminal progenitor nature of MMTV‐PyMT tumors." (PMID 35611998, 2022). "The expression levels of cancer stem cell markers CD24 and CD29 were lower in doxorubicin-treated mice than in controls, with lower expression in mice treated with doxorubicin plus FO/Se supplements than with doxorubicin alone." (PMID 36483592, 2022). "Treatment of the anti-CD24 neutralizing antibody had little effect on the invasive activity of SP0926 cells, as CD24 expression levels are very low in this derivative cancer cells." (PMID 36302783, 2022). "We found that plasticity, which re-programmed CD44(-) differentiated cancer into CD24(+)CD44(+)EpCAM(+) CICs, was inhibited when JAG1 was neutralized." (PMID 35673567, 2022).
cancer (continued). "In cancer cell lines, CD24 also activates β1 integrin, which in turn promotes cell adhesion to extracellular matrix, migration, and metastasis." (PMID 36294907, 2022). "It was shown that CD24 expression, a receptor expressed on the surface of metabolically active cells including cancer cells is essential to ZIKV oncolytic activity." (PMID 35163212, 2022). "CD24 has been reported as a marker of several normal tissue‐derived stem/progenitor cells and cancer stem cells." (PMID 35716037, 2022). "CD24 is a highly glycosylated cell-surface protein and can be detected in various cell types, including cancer cells, exerting an inhibitory effect in autoimmune diseases, noxious inflammation, and cancer biology." (PMID 36497444, 2022). "It was found that CD24 is an anti-phagocytic signal, which protects cancer cells from macrophage attacks expressing Siglec-10." (PMID 35330093, 2022). "Its multifaceted role in both the regulation of the immune response and tumorigenesis has made CD24 a compelling target for the immunotherapy of cancer." (PMID 36013184, 2022). "In further experiments, we found that inhibition of miR-328-3p dramatically increased the proportion of CD44 + CD24-cells (cancer stem-like cells)." (PMID 34045663, 2022). "CD24 is a glycosylated protein highly expressed in numerous cancer and cancer stem cells and involved in the development, invasion, and metastasis of cancer cells." (PMID 35409274, 2022). "In this study, we deciphered the molecular and (epi)genetic mechanisms regulating expression of CD24, a highly glycosylated signaling molecule upregulated in many cancers." (PMID 34293822, 2022). "Cancer stem cells from either human GC cell lines or tumor tissues were isolated using cell surface markers such as CD24, CD44, CD54, CD71, CD90, CD133, Lgr5, ALDH1, EpCAM, and CXCR4." (PMID 36176765, 2022). "CD24 also affects the proliferation of cancer cells and their adhesion to fibronectin, collagen, and laminin." (PMID 36010245, 2022). "In cancer microenvironment, CD24 regulates cell migration, invasion and proliferation, also known as a biomarker of poor cancer prognosis." (PMID 36551739, 2022). "As a P-selectin ligand CD24 plays also a significant role in the oncogenesis of many types of cancers, allowing neoplastic cells to roll on the endothelial cells and metastasize." (PMID 36010245, 2022). "Specifically, antibody-mediated targeting of CD24 robustly enhanced the phagocytic uptake of MCL cells yielding over 90% removal of CD24 expressing MCL cancer cells." (PMID 35625912, 2022). "CD24 also plays a potential role in cancer migration in various cancer types along with prognostication." (PMID 36031601, 2022). "The expression of cancer stem cell markers CD24 and CD44, cytokeratins, and vimentin was investigated by immunofluorescence." (PMID 35563359, 2022). "CD24 is a highly expressed, anti-phagocytic signal in several cancers and demonstrates therapeutic potential for CD24 blockade in cancer immunotherapy." (PMID 36315425, 2022). "In this review, we summarize current evidence and future perspectives on CD24 as a potential target for cancer immunotherapy." (PMID 36013184, 2022). "This concept was further supported by the positive correlation of CEP192 with characteristic onco-fetal genes, also known as cancer stem cell markers, including CD24, SOX9, CD47, and POU5F1 (OCT4)." (PMID 36238304, 2022). "Recently, the interest in therapeutic targeting of CD24 was revitalized by its reported innate immune checkpoint function in carcinoma." (PMID 35625912, 2022). "Similar to MCL cell lines and regardless of the high expression of CD47, the specific increase in phagocytosis in carcinoma lines was significantly higher for CD24 than for CD47 antibody treatment for all CD24+ cells." (PMID 35625912, 2022). "CD24, also known as heat-stable antigen in mouse, is significantly upregulated in different cancers compared to their benign counterparts." (PMID 33588867, 2021).
cancer (continued). "We have highlighted the role of the cancer stem cell marker CD24 in the dynamics of cell plasticity and the acquirement of drug resistance." (PMID 34426608, 2021). "Our results demonstrated that the average levels of CD24/CD11b in healthy patients (21.7 ± 9.0) were statistically significantly lower compared to levels of CD24/CD11b in cancer patients (29.5 ± 18.7, p < 0.001)." (PMID 34442367, 2021). "Herein, we describe a method for the IN-mediated induction of cell death, targeted to CD24-expressing cancer cells." (PMID 33958722, 2021). "CD44+ ESA+ CD24+ cancer cells demonstrate characteristics of stem cells including increased developmental signaling pathway (including SHH) leading to chemoresistance." (PMID 33836674, 2021). "CD24 is a cell surface protein that is expressed in putative stem cells and is overexpressed in various malignant tumors." (PMID 35723384, 2021). "CD24 is highly expressed in a large variety of human cancers and is involved in processes such as proliferation, invasion, chemosensitivity, and metastasis of various types of cancer." (PMID 33467499, 2021). "High expression levels of CD24 have been identified in various types of cancers, including hematological malignancies, and indicate a poor prognosis and a more aggressive course of the disease." (PMID 34442367, 2021). "CD24 is highly expressed in ovarian, breast, prostate, bladder, kidney, non-small cell, colorectal, and other human cancers." (PMID 34575716, 2021). "Through these interactions, CD24 mediates processes such as cancer development, invasion, and metastasis." (PMID 34360932, 2021). "CD24 is an adhesion molecule anchored by glycosyl-phosphotidyl-inositol and dysregulated in several cancer subtypes, including renal, breast, ovarian, lung, and pancreatic cancers." (PMID 33806857, 2021). "CD24 is a heavily glycosylated GPI-anchored surface protein expressed on cancer cells, particularly in ovarian cancer and triple negative breast cancer, relative to healthy tissue." (PMID 34638388, 2021). "As an important “don't eat me” signaling molecule, CD24 binds to Siglec‐G (mice) or Siglec‐10 (humans) in cancer cells, triggering the immune escape reactions." (PMID 34363319, 2021). "We further identified an increase in label retaining and CD44 + CD24− expressing cells, which are markers frequently used to characterize drug resistant cancer stem cells, in these cultures." (PMID 34561423, 2021). "CD24 is often overexpressed in cancer, and its overexpression is correlated with poor prognosis in various cancer types." (PMID 33919517, 2021). "The majority of prostate cells in cancer specimens had CD44-/CD24- phenotype with reduced CD44-/CD24+ cell fraction compared to BPH." (PMID 34019593, 2021). "In in-vivo and in-vitro cancer models, it was suggested that CD24 promotes colorectal, cervical, and breast cancer cell proliferation." (PMID 33562144, 2021). "CD24 was recently investigated as a potential cancer stem cell (CSC) marker, although the results were ambiguous." (PMID 33806857, 2021). "And the results showed a higher expression of JUP and ITGB4 in cells expressing CD44 or CD24, which were cell markers of cancer stem cells." (PMID 34402716, 2021). "Studied most extensively in the field of cancer research, CD24 is suggested to be a marker for circulating cancer stem cells (CSCs), a small subset of cancer cells that retains differentiation potency and low proliferative profile." (PMID 33915986, 2021). "The average levels of CD24/CD11b in healthy patients (21.7 ± 9.0) were statistically significantly lower compared to in cancer patients (29.5 ± 18.7, p < 0.001)." (PMID 34442367, 2021). "CD24 is considered a cancer stem cell marker and is of critical importance in cancer, involved in cancer cell proliferation and metastasis, as well as immune suppression and escape." (PMID 34360932, 2021).
cancer (continued). "CD24 is emerging as a potential marker for personalized treatments of cancer, and we previously showed the beneficial effect of CD24 antigen-based treatment in a cancer model." (PMID 33562144, 2021). "CD24 is a small, heavily glycosylated protein, that is considered to be a cancer biomarker, as it is expressed mostly in cancer cells and very rarely in normal cells." (PMID 33958722, 2021). "The other previous study of BCSC transcriptomes also used the markers CD44 high/CD24 low in two HER2-positive/ER-negative cancers." (PMID 34253873, 2021). "In determining the specificity and sensitivity of the CD24/CD11b test and its ability to discriminate between patients with cancer from healthy individuals, area under the receiver operator curve (ROC), cutoff value was derived." (PMID 34442367, 2021). "Recently, disseminating hybrid E/M CSCs that co-express EpCam, Vimentin, and CD24 have been observed in human cancer specimens, thus proving that a hybrid E/M CSC-like state is predictive of metastasis." (PMID 34830900, 2021). "CD24/CD11b expression in 122 cancer patients having different types of hematological cancers was analyzed." (PMID 34442367, 2021). "CD24 has been identified as one of the most important CSC markers in several cancers, including ovarian and colorectal cancers." (PMID 34064635, 2021). "CD24 is a surface protein expressed mostly in cancer cells and is very rarely found in normal cells." (PMID 33958722, 2021). "Like Siglec-15, Siglec-10 is also expressed on TAMs and transmits “don’t eat me signals” upon binding to CD24, a cancer-expressed sialoglycoprotein." (PMID 34064396, 2021). "Real-time PCR showed that CD44, N-cadherin, and β-catenin mRNAs were highly expressed in cancer tissues, while CD24 mRNAs were low in expression compared with adjacent tissues (P < 0.05)." (PMID 34789199, 2021). "Sensitivity and specificity values of the CD24 blood test indicated feasibility of CD24/CD11b to serve as a cancer screening test for further development of hematological neoplasia." (PMID 34442367, 2021). "Directed biological therapies that block CD24 are thus studied as promising novel cancer treatment modalities, using monoclonal antibodies, chimeric molecules or siRNA." (PMID 33915986, 2021). "These specific cancer cells are called cancer stem cells (CSCs), which are detected mainly with the expression of specific cell surface markers (CD24+, CD44+, or CD133+; alone or combined expression)." (PMID 34206730, 2021). "In cancer, by interaction with endogenous Siglec-10 on TAMs, CD24 protects cancer cells from phagocytosis by acting as a phagocytic inhibitor (a“do not eat me” signal)." (PMID 33499388, 2021). "Several studies report the enrichment of cancer stem cell features such as high expression of the CD44+/CD24- immunophenotype in these cells." (PMID 34367990, 2021). "This corroborates with our in vitro data in which 4bt considerably decrease cancer stem cells (CSC) represented by CD44+/CD24- population." (PMID 34548908, 2021). "Studies have shown that CD24 promotes cancer cell adhesion, growth, proliferation, invasion, and metastasis, while inhibits cancer cell apoptosis." (PMID 34363319, 2021). "The data from the current study indicated that a higher frequency of CD44-/CD24- cancer cells, like higher frequency of CSCs, was one of the independent risk factors for delayed distant metastasis and worse DFS in this population." (PMID 34318746, 2021). "Univariate and multivariate analyses indicated that high frequency of CD44-/CD24- cancer cells or CSCs, positive lymph node metastasis, higher N stage, and TNBC were independent risk factors for poor DFS." (PMID 34318746, 2021). "The average frequency of CD44-/CD24- cancer cells in all samples was 19.7% with a median value of 19.5%." (PMID 34318746, 2021).
cancer (continued). "Currently, we are developing the next generation platform, consisting of a new lentiviral vector that will comprise both parts, i.e., it would carry the INS peptide and be targeted only to cancer cells by means of an anti-CD24 scFv." (PMID 33958722, 2021). "On the other hand, little is known about the role of CD24 in canine PC, making any possible comparative applicability of potential CD24-focused cancer therapies difficult." (PMID 33806857, 2021). "In order to investigate the effect of CD24 upon the acquired tumorigenicity of miR-146a expressing cancer cells in vivo, we examined xenograft tumors generated from SCC084/miR-146a cells harboring CD24 expression construct." (PMID 34712602, 2021). "CD24 has been identified as a CSC marker in a wide range of cancers and has been detected in B cell precursors, neutrophils, neuronal cells, and various epithelial cells." (PMID 34064635, 2021). "GLI1 is overexpressed in BCSCs characterized by CD44+/CD24- phenotype compared to other cancer cells and is important for EMT and metastatic progression." (PMID 34889737, 2021). "Antibody-mediated blockade of the CD24–Siglec-10 interaction robustly augments the phagocytosis of CD24+ cancer cells by macrophages." (PMID 34064396, 2021). "Our results suggested that SPNs affect both PANC-1 cancer cells and PANC-1 cancer stem-like cells through decreasing CD surface markers CD24, CD44, and CD133." (PMID 34094034, 2021). "In this context, it would be of interest to evaluate the cytotoxic activity of Mob-MDM(LPS/IFNγ) in vitro against CD24-expressing human cancer cell lines as well as in vivo in humanized mouse cancer models." (PMID 34281268, 2021). "When compared with those in low-grade PCa tissues with Gleason scores of 6 (control), the ALDH, CD44, CXCR4 and CD24 protein levels were generally elevated in para-carcinoma tissues." (PMID 34247196, 2021). "In this study, which has used THP-1 cells or blood monocytes, physical co-culturing of monocytic cells with cancer cells has given rise to elevated proportions of CSCs (CD44+/CD24− and ALDH+) and the cancer cells have gained some EMT characteristics." (PMID 33585241, 2020). "CD24‐/CD44+ cancer cells show more significant stemness and resistance than CD24+/CD44+ cancer cells, and there is inherent resistance to radiotherapy." (PMID 32991066, 2020). "Another approach to stimulate the immune system and target cancer stem cells is the exploitation of engineered third-generation CD24-chimeric antigen receptor (CAR)-expressing natural killer cells (CD24-CAR-NK cells)." (PMID 33260974, 2020). "We compared the expression of putative cancer stem cell markers (CD24, CD44, CD117, ROR1, and CD133) of HGSC [31134503] at P2 and P8, as well as two HGSOC cell lines." (PMID 32035490, 2020). "PCSCs express markers of cancer stem cells (CSCs) including CD24, CD133, CD44, and epithelial specific antigen as well as the drug transporter ABCG2 grow as spheroids in a defined growth medium." (PMID 34841087, 2020). "CD24 is expressed on hematopoietic cells, immature neuronal cells, and numerous types of cancer cells." (PMID 32394616, 2020). "Another recent study confirmed that nicotine-treated MCF7 cells exhibited changes in cell structure, cellular motility (related to the relocation of F-actin) and an enhanced MCF7 CD44 + CD24- cancer stem cell population." (PMID 33203443, 2020). "The decrease of HIF-1α or CD24 expression mediated by shRNA reduces the survival rate of cancer cells in vivo and in vitro at the growth level of primary and metastatic tumors." (PMID 32765491, 2020).